LINC00504 (long independently transcribed non-coding RNA 504)
Gene: Long non-coding RNA gene on chromosome 4 (14,470,465 to 14,888,169, reverse strand). Ensembl gene ENSG00000248360.
Diseases named in the same sentence as LINC00504 in open-access papers:
LINC00504 is named in the same sentence as 4 diseases in open-access papers, as found by Europe PMC text mining. Sharing a sentence is not in itself a finding about the gene and the disease. The quoted sentences say what the papers report.
breast carcinoma (2 papers, 2021). "RFX5 can strongly increase transcriptional activity of LINC00504 and the latter is upregulated in breast cancer." (PMID 35071020, 2021).
colon cancer (1 paper, 2021). "In the same study, LINC00504 silencing also decreased xenograft tumor volume, suggesting that LINC00504 promoted colon cancer development both in vitro and in vivo." (PMID 33670895, 2021).
lymph node metastasis (1 paper, 2025). "Elevated levels of LINC00504 correlate with an increased tumour size, advanced stage, and lymph node metastasis, indicating a negative impact on the prognosis." (PMID 40535770, 2025).
tumor (2 papers, 2021 to 2025). "Six hits in five genes [AK3 (rs378117), TRPM3 (rs1329774 and rs4745058), CDH4 (rs2427043), LINC00504 (rs76228864), and GRIN2D (rs76754767)] were associated with a risk of tumour progression, whereas variants in HPGD (rs45593131) and RC3H2 (rs2792999) were suggested as protective factors." (PMID 40535770, 2025).